ENSG00000258064 (novel protein)
Gene: Protein-coding gene on chromosome 12 (71,674,204 to 71,698,968, forward strand). Ensembl gene ENSG00000258064.
Genetic constraint (gnomAD): Missense variants: 82 observed, 104.82 expected, observed/expected ratio (o/e) 0.78, 90% interval 0.65 to 0.94. Synonymous variants: 32 observed, 37.33 expected, observed/expected ratio (o/e) 0.86, 90% interval 0.65 to 1.15.